TH (tyrosine hydroxylase)
Diseases named in the same sentence as TH in open-access papers (continued):
Sharing a sentence is not in itself a finding about the gene and the disease.
neuroblastoma (103 papers, 2006 to 2025). Neuroblastoma (NB) is the most common solid, extracranial childhood tumor. "MRD detection in BM samples evaluated by a set of five markers (CHRNA3, DDC, GAP43, PHOX2B, and TH) was associated with poor outcome in patients aged over 1 year with stage 4 neuroblastoma." (PMID 31214500, 2019). "In contrast to these reports, positive TH mRNA in PBSC samples predicted a lower 2-year OS in high-risk neuroblastoma patients." (PMID 31214500, 2019). "When BM samples are evaluated by a set of five markers (CHRNA3, DDC, GAP43, PHOX2B, and TH), unfavorable outcome in localized neuroblastoma patients is associated with the detection of more than one positive-marker." (PMID 31214500, 2019). "We have previously shown that transgenic mice co-expressing an active ALKF1174L mutation with MYCN via the tyrosine hydroxylase promoter potentiates neuroblastoma development characterized by earlier onset, higher penetrance and enhanced lethality." (PMID 27483357, 2016). "In a recent study, Lee and colleagues evaluated the clinical significant of TH mRNA transcripts levels in the peripheral blood of patients with neuroblastoma demonstrating that TH expression was associated with high-risk features, advanced stage and worse outcome." (PMID 29930753, 2018). "Transgenic mice with tyrosine hydroxylase promoter-driven expression of MYCN in the neural crest developed neuroblastoma, indicating that MYCN amplification alone is sufficient to induce the development of this cancer." (PMID 39802403, 2025). "Neuroblastoma cells in the HIF2α-induced tumors, exhibiting high levels of HIF2α also have high levels of TH, but low levels of Ki67, whereas control tumors exhibit high levels of Ki67 and low levels of TH." (PMID 41118218, 2025). "The MN9D cell line is a fusion of N18TG2 neuroblastoma cells and mouse dopaminergic midbrain neurons, and therefore endogenously expresses tyrosine hydroxylase protein." (PMID 39456033, 2024). "We have shown that the tumors that arise in the IRG in this transgenic fish model are small, round, blue cell tumors expressing tyrosine hydroxylase and synaptophysin, which are markers of human neuroblastoma." (PMID 37183825, 2023). "SH-SY5Y human neuroblastoma cells is a widely-used PD model which mimics some aspects of DA neuron phenotype, such as the expression of tyrosine hydroxylase, dopamine-β-hydroxylase, and dopamine transporter." (PMID 35912090, 2022). "Attempts to enrich neuroblastoma CTCs have been largely limited to capture-based methods relying on cellular expression of TH, PHOX2B, NCAM and GD2 synthase, though these inherently introduce a selection bias." (PMID 36176417, 2022). "SH-SY5Y neuroblastoma cells exposed to the hypoxia mimetic agent deferoxamine (DFO) exhibit a neuron-like tyrosine hydroxylase (TH) expressing phenotype." (PMID 34557995, 2022). "Human neuroblastoma SH-SY5Y cells express tyrosine hydroxylase (TH), a key enzyme that converts tyrosine to dihydroxyphenylalanine (DOPA), and therefore, important during the production of neurotransmitters such as dopamine, norepinephrine, and epinephrine." (PMID 35264673, 2022). "Amongst these genes were neuroblastoma-associated genes NTRK1, BCL11A, TH and CHGB, as well as HMX1, a transcription factor on chromosome 4 that is a master regulator of neural crest development." (PMID 36071103, 2022). "Large cells measuring 14-16 μm were captured, which expressed known neuroblastoma markers GD2 synthase, PHOX2B and TH – the primers having been first verified by demonstrating their expression in 7 neuroblastoma cell lines." (PMID 36176417, 2022). "In fact, it has been reported that TH is constitutively expressed at very low levels in SH-SY5Y neuroblastoma cells and significantly increases after 3-day treatment with 10 μM RA." (PMID 36313013, 2022). "In the human neuroblastoma cell line SK-N-SH, ascorbic acid (200 microM) led to enhanced expression (three-fold) of tyrosine hydroxylase (TH) after 5 days of treatment." (PMID 34680401, 2021).
neuroblastoma (continued). "Using pathological and immunohistochemical analyses with antibodies against neuroblastoma markers, such as Tyrosine Hydroxylase (TH) and HuC, widespread metastasis were detected in the orbit, gill, spleen, distal portion of kidney and heart." (PMID 33800887, 2021). "Further along this line, expression of tyrosine hydroxylase, an established marker for neuroblastoma cells, was investigated by immunofluorescent staining." (PMID 32860155, 2021). "The NB5 assay uses RT-PCR to detect the co-expression of five mRNAs from the neuroblastoma-associated genes, CHGA, DCX, DDC, PHOX2B, and TH." (PMID 34055604, 2021). "The induction of the dopaminergic phenotype of SH-SY5Y neuroblastoma cells, described in the Methods section, was analyzed by contrast phase microscopy, Tyrosine Hydroxylase (TH) expression, dopamine production and immunofluorescence." (PMID 32155131, 2020). "SH-SY5y cells are human neuroblastoma that possesses many features of dopaminergic neurons, including the expression of tyrosine hydroxylase and dopamine transporter." (PMID 32120831, 2020). "Study has illuminated that ascorbic acid (AA) stimulates dopamine synthesis and expression of tyrosine hydroxylase in human neuroblastoma cells." (PMID 33281897, 2020). "A set of three markers (DCX, PHOX2B, TH) was identified by genome-wide gene expression microarray analyses of 32 neuroblastoma tumors and pooled PB sample from 24 healthy volunteers followed by selecting genes not expressed in pooled PB samples." (PMID 31214500, 2019). "In connection to Pitx3 mRNA expression, the literature has shown that Pitx3 interacts with the promoter of the TH gene improving its transcription in Neuro2A neuroblastoma cells." (PMID 31547185, 2019). "While amplification of TH mRNA was shown to detect neuroblastoma cells in BM and PB samples, low level of its expression in normal BM cells initially limited its specificity." (PMID 31214500, 2019). "High levels of DCX, PHOX2B, or TH mRNAs in BM and PB samples at diagnosis or BM samples after induction therapy predicted poor outcome in children with stage 4 neuroblastoma." (PMID 31214500, 2019). "Transgenic mice where the human MYCN cDNA is placed in front of the tyrosine hydroxylase promoter (Th-MYCN) spontaneously develop neuroblastomas which are morphological and phenotypical similar to human high-risk neuroblastomas." (PMID 30760980, 2019). "In the absence of tumor-specific mRNA, the rate-limiting enzyme in catecholamine biosynthesis, TH, was evaluated as the first neuroblastoma-associated mRNA to detect MRD in neuroblastoma patients." (PMID 31214500, 2019). "These 3D spheroids retain expression of neuroblastoma markers chromogranin A, synaptophysin and tyrosine hydroxylase and retain their tumorigenic and spontaneous metastatic capacity upon orthotopic injection." (PMID 28924803, 2018). "Bax-dependent neuronal apoptosis in human neuroblastoma cells, as well as α-synuclein aggregates and tyrosine hydroxylase turnover in human neuroblastoma cells." (PMID 30740124, 2018). "DNA Ligase III, Ligase I, and PARP1 silencing significantly decreased neuroblastoma markers expression (TH, Phox2b, and TRKB)." (PMID 29238067, 2017). "The PHOX2B-mediated downregulation induced an upregulation of TH, a marker for bad prognosis in neuroblastoma." (PMID 26840262, 2016). "Using immunocytochemistry, we showed that bone-marrow mononuclear cell (BMMC)-conditioned medium can induce tyrosine hydroxylase expression in neuroblastoma cells, which is similar to the effect of retinoic acid." (PMID 23551916, 2013). "First, we evaluated the effect of cells of the human BMMC fraction on the expression of TH protein in neuroblastoma cells by culturing SH-SY5Y cells in BMMC-conditioned medium." (PMID 23551916, 2013). "With estimated concentration of 35 ± 2 × 104 cells/ml for staining, the results showed that BMMC-conditioned medium can induce TH protein expression in neuroblastoma cells, which is similar to the effect of ATRA." (PMID 23551916, 2013).
neuroblastoma (continued). "TH-MYCN transgenic mice with the MYCN oncogene in the germline, driven by the tyrosine hydroxylase (TH) promoter, develop a tumour phenotype which closely resembles human neuroblastoma." (PMID 21698133, 2011). "The neuroblastoma antigen tyrosine hydroxylase (TH) is another promising candidate for immunotherapy of neuroblastoma." (PMID 21197271, 2010). "A murine model of neuroblastoma has been established by targeted expression of the human MYCN oncogene in neuroectodermal cells under the control of rat tyrosine hydroxylase promoter (TH-MYCN)." (PMID 19730731, 2009). "We then used PCR to detect the v-myc gene present in HB1.F3.C1 cells and RT-PCR to detect tyrosine hydroxylase (TH), a neuroblastoma cell marker." (PMID 17183650, 2006). "qPCR showed that CAMK2G knockdown by RNA interference and 6‐OHDA–induced injury inhibited TH transcription in PMA‐differentiated human neuroblastoma (SH‐SY5Y) cells, which constitutively express TH and are morphologically, physiologically and biochemically similar to adrenergic neuron." (PMID 38544478, 2024). "Interestingly, analysis of TH expression revealed that compared to differentiated SH-SY5Y neuroblastoma, overexpression of alpha-synuclein resulted in a 72% decrease in TH mRNA levels for the α-synWT and a 94% decrease in the α-synA53T cells." (PMID 38203538, 2023). "Likewise, they demonstrated that the agonist for ERRγ, GSK4716, increases DAT and TH expression in differentiated SH-SY5Y neuroblastoma cells." (PMID 35982091, 2022). "However, on the MN9D line (hybrid neuroblastoma-immortalized DA mesencephalic neurons from C57Bl/6 mice embryos), it was shown that P19-TH binds to chaperone proteins of the 14-3-3 family, which can lead to an increase in TH activity." (PMID 35741664, 2022). "This is in contrast with previous reports that demonstrate that GDNF can increase dopamine levels via the regulation of TH gene expression in a Ret-dependent response in human neuroblastoma cell lines and in grafts of human ESC-derived DaNs into an environment of GDNF overexpression." (PMID 34239871, 2021). "Interestingly, in vitro studies with human neuroblastoma SH-SY5Y cells have shown that 24S-HC increases the levels of tyrosine hydroxylase (TH), the rate-limiting enzyme in dopamine synthesis, while 26-HC increases levels of α-synuclein and induces apoptosis." (PMID 30936243, 2019). "We have shown VITD elevates TH mRNA and protein in neuroblastomas in culture." (PMID 29950608, 2018). "Indeed, serotonin treatment of undifferentiated human neuroblastoma LAN-5 cells led to a decrease in TH activity." (PMID 30127714, 2018). "It is still to be determined whether the upregulation of TH is involved in promoting the malignant behavior of neuroblastoma cells." (PMID 26840262, 2016). "A strong link to a neural crest-derived cell of origin for neuroblastoma was established when mice overexpressing MYCN in neural crest cells under the tyrosine hydroxylase promoter were shown to develop neuroblastoma-like tumors, specifically in the paraspinal sympathetic ganglia." (PMID 26222553, 2015). "Evidence has indicated that human SH-SY5Y neuroblastoma cells changed into neuron-like phenotypes with reduced proliferation by all-trans retinoic acid (ATRA), and treatment with RA increased protein expression of tyrosine hydroxylase (TH) in neuroblastoma cells." (PMID 23551916, 2013). "We also uncovered a decrease in the expression of many other PKA substrates in HPRT-deficient human and mouse neuroblastoma cell lines, including tyrosine hydroxylase (TH) (Ser40) and DARPP-32 (Thr34) (data not shown) that are also important effectors of neuronal function." (PMID 23691025, 2013). "To map the expression of EPAS1 in neuroblastoma in situ, we performed RNA-scope with probes for EPAS1, TH, and the endothelial marker ENG (Endoglin) in tumors of different stages." (PMID 41118218, 2025).
neuroblastoma (continued). "To investigate the functional importance of PA2G4 in MYCN-driven neuroblastoma in vivo, we utilized the Th-MYCN transgenic mouse model, in which the human MYCN gene is expressed under the control of the tyrosine hydroxylase promoter." (PMID 41002386, 2025). "We confirmed that the commonly used neuroblastoma MRD markers (including PHOX2B, TH, CHRNA3, GAP43) are rarely expressed in mesenchymal neuroblastoma cell lines." (PMID 39722049, 2024). "Human neuroblastoma SH-SY5Y cells exhibit neuroblast-like characteristics similar to those of catecholaminergic neurons and express markers such as tyrosine hydroxylase (TH) and dopamine-β-hydroxylase (DBH)." (PMID 39607552, 2024). "To study cfRNA in limited volume samples of pediatric patients with neuroblastoma, we first designed and optimized a multiplex ddPCR which included the neuroblastoma-specific targets PHOX2B, CHRNA3 and TH, and GUSB as a reference gene." (PMID 37046768, 2023). "The most prominent MYCN-driven tumor models mimic human neuroblastoma, in which MYCN expression, driven by tyrosine-hydroxylase (TH)- or dopamine-β-hydroxylase- (Dbh)-cre, leads to the development of aggressive tumors, modeling the human disease." (PMID 38001143, 2023). "The mRNA content was determined using several multiplex droplet digital PCR (ddPCR) assays for a neuroblastoma-specific gene panel (PHOX2B, TH, CHRNA3) and a cell cycle regulation panel (E2F1, CDC6, ATAD2, H2AFZ, MCM2, DHFR)." (PMID 37046768, 2023). "The presence of neuroblastoma-specific mRNA in the cellular compartment of blood and bone marrow, such as PHOX2B, TH and CHRNA3, has been shown to correlate with outcome, enabling response monitoring in patients with high-risk disease." (PMID 37046768, 2023). "Consistent with this, human MYCN transgene expression driven by rat tyrosine hydroxylase (TH) promoter in the transgenic TH-MYCN mice, is sufficient to recapitulate many of the features of human neuroblastoma." (PMID 37958555, 2023). "To confirm that TGF-β1 suppresses the expression of TH, we treated SH-SY5Y cells—human neuroblastoma cells possessing features of dopaminergic neurons—with TGF-β1 and measured the level of TH using Western blot analysis and real-time PCR." (PMID 33806649, 2021). "An in vitro study also showed that the activation of AhR can induce tyrosine hydroxylase (TH) enzymes, which leads to increased dopamine and L-DOPA in murine neuroblastoma cells." (PMID 34685709, 2021). "SH-SY5Y cells are derived from human neuroblastoma cell lines and have moderate TH activity, while PC12 cells have high TH activity." (PMID 33646533, 2021). "Further, different mRNA markers are being explored for MRD detection in blood (PHOX2B, TH, DDC, DBH, and CHRNA3) and bone marrow (PHOX2B, TH, DDC, CHRNA3, and GAP43) from neuroblastoma patients." (PMID 31897843, 2020). "Here, we also report an increase in TUBB3, MAP2, TH and DAT levels during neuroblastoma SH-SY5Y rho0 cell differentiation." (PMID 31717322, 2019). "The combined signature of five markers (CHGA, DCX, DDC, PHOX2B, and TH) expression in BM and PB was correlated with PFS of relapsed/refractory neuroblastoma." (PMID 31214500, 2019). "In initial studies, we used differentiated SH-SY5Y neuroblastoma cells that express markers of dopaminergic neurons such as DAT and TH." (PMID 28828398, 2017). "The increased TH expression, a marker for bad prognosis in neuroblastoma, suggested an involvement of PHOX2B in shaping the malignant phenotype of neuroblastoma cells." (PMID 26840262, 2016). "MLN8237 is effective in MYCN-driven transgenic mouse models of neuroblastoma (TH-MYCN), in which high-level expression of MYCN is driven in neural crest by a tyrosine hydroxylase (TH) promoter." (PMID 25785590, 2015). "Compared with the existing MYCN-driven mouse model of neuroblastoma, which expresses a human MYCN cDNA under the control of a rat tyrosine hydroxylase promoter, the novel LSL-MYCN;Dbh-iCre bears several advantages." (PMID 25174395, 2015).
neuroblastoma (continued). "In line with previously published analyses of HOXC9 in neuroblastoma cells, we found a significant up-regulation of genes involved in neuronal differentiation pathways such as DNER, NEFL, DBH, TH, RET, MAP2 and NPY." (PMID 25406647, 2014). "The RMS component was strongly positive for myogenin and desmin by immunohistochemical staining, while the neuroblastoma component was stained with neural markers such as PGP9.5 and tyrosine-hydroxylase, CD56, synaptophysin, and S100." (PMID 25405050, 2014). "The TH-MYCN transgenic mouse is the most widely used murine model of human neuroblastoma, in which a human MYCN oncogene is targeted to neuroectodermal cells of developing mice under the influence of the rat tyrosine hydroxylase promoter." (PMID 19730731, 2009). "In this study, we showed that TCDD not only increases TH gene expression but also the amounts of dopamine and L-dopa in TCDD-exposed murine neuroblastoma cells (Neuro2a)." (PMID 19500377, 2009). "Additionally, like Paraquat, Maneb increased the level of a-synuclein (a-syn), a neuronal protein critical for normal brain function, and altered the tyrosine hydroxylase and the protein turnover in SH-SY5Y human neuroblastoma cells." (PMID 35270318, 2022). "Since PHOX2B and TH showed the highest relative expression across the panel of cell lines compared to non-neuroblastoma cell line AGS, the separation method and primers were then used to discriminate neuroblastoma from blood cells in clinical samples." (PMID 36176417, 2022). "In 4 patients with clinically-proven metastatic disease in their bone marrow aspirates (NB4, NB17, NB19, NB25), DTCs stained positive for neuroblastoma immunohistochemical markers PHOX2B and TH, and DTC-enriched fractions from BMAs also expressed elevated levels of PHOX2B and TH on RT-qPCR." (PMID 36176417, 2022). "Significant expression of (nor-)adrenergic (“NOR”) markers (i.e., CHGA, CHGB, DBH, TH, PHOX2A, and PHOX2B) is common for healthy sympatho-adrenal cells and tumor NOR populations identified in low-risk neuroblastoma cases (FDR < 0.01, Welch’s t-test)." (PMID 34493726, 2021). "Studies comparing HIF protein expression with the expression of hypoxia driven genes at the cellular level in tumor sections have shown that HIF-1α/HIF-2α expression is not always congruent with an expression of established hypoxia driven genes such as TH and IGF-2 in neuroblastoma." (PMID 33467498, 2021). "In SK-N-MC neuroblastoma cells, NPY decreases tyrosine hydroxylase mRNA levels." (PMID 32246073, 2020). "Furthermore, in normal mice, i.c.v. microinjection with orexin-A also increased the protein levels of BDNF and TH in the striatum, which was further confirmed in SH-SY5Y human dopaminergic neuroblastoma cells." (PMID 30524223, 2018). "These neuroblastoma spheroids were derived from naturally occurring mouse abdominal and thoracic neuroblastomas from transgenic mice, in which the human MYCN gene was constitutively expressed under the control of the rat tyrosine hydroxylase promoter (TH-MYCN mouse)." (PMID 37240360, 2023). "A reduced expression level of Oct4, SOX2 and NESTIN was found, whereas TrkA, TH, MAP2 and TUJ1 was increased in USP3-silenced cells, suggesting that USP3 downregulation might impair self-renewal capacity in neuroblastoma." (PMID 37170124, 2023). "In 2017, the International Neuroblastoma Response Criteria Bone Marrow Working Group recommended the collection of both bilateral BM biopsies and aspirates and their analysis with immunohistochemistry for GD2 and RTqPCR for tyrosine hydroxylase and paired-like homeobox 2B (PHOX2B)." (PMID 34623519, 2022). "The biochemical differentiation profile of neuroblastoma cells overexpressing TMODs showed a significant increase of MAP2 and GAP43, mimicking then the “neuronal differentiation” obtained by retinoic acid, and an overall decrease of TH, DBH and CgA mRNA expression levels." (PMID 29930753, 2018).